IFNL3 (interferon lambda 3)
Description:
Cytokine with antiviral, antitumour and immunomodulatory activities. Plays a critical role in the antiviral host defense, predominantly in the epithelial tissues. Acts as a ligand for the heterodimeric class II cytokine receptor composed of IL10RB and IFNLR1, and receptor engagement leads to the activation of the JAK/STAT signaling pathway resulting in the expression of IFN-stimulated genes (ISG), which mediate the antiviral state. Has a restricted receptor distribution and therefore restricted targets: is primarily active in epithelial cells and this cell type-selective action is because of the epithelial cell-specific expression of its receptor IFNLR1. Seems not to be essential for early virus-activated host defense in vaginal infection, but plays an important role in Toll-like receptor (TLR)- induced antiviral defense. Plays a significant role in the antiviral immune defense in the intestinal epithelium. Exerts an immunomodulatory effect by up-regulating MHC class I antigen expression.
Synonyms: IFN-lambda-3; IL-28B; IL-28C; IL28B; IL28C; IFN-lambda-4
Tractability: Small molecule: it has a high-quality binding pocket. Antibody: UniProt places it where antibodies can reach, with high confidence; its Gene Ontology location is reachable by antibodies, with high confidence; UniProt predicts a signal peptide or a membrane-spanning region.
Gene: Protein-coding gene on chromosome 19 (39,243,455 to 39,245,250, reverse strand). Ensembl gene ENSG00000197110.
Subcellular location: Secreted
Pathways (Reactome):
Immune System: Interleukin-20 family signaling
Gene Ontology:
Molecular function: signaling receptor binding; cytokine activity
Biological process: cellular response to virus; defense response to virus; innate immune response; negative regulation of viral genome replication; type III interferon-mediated signaling pathway; cell surface receptor signaling pathway via JAK-STAT; positive regulation of immune response
Cellular component: extracellular region
Genetic constraint (gnomAD): Loss-of-function variants: 17 observed, 17.27 expected, observed/expected ratio (o/e) 0.98, 90% interval 0.67 to 1.47. The upper end of that interval is the gene's LOEUF score, 1.47, which puts it in group 6 of 6, group 1 being the genes least tolerant of losing a copy. Missense variants: 254 observed, 249 expected, observed/expected ratio (o/e) 1.02, 90% interval 0.92 to 1.13. Synonymous variants: 115 observed, 112.46 expected, observed/expected ratio (o/e) 1.02, 90% interval 0.88 to 1.19.
Homologues: Orthologues: chimpanzee IFNL3 (96% identical), macaque IFNL3 (94% identical), dog IFNL3 (72% identical), pig IL28B (69% identical), mouse Ifnl2 (65% identical), mouse Ifnl3 (62% identical), tropical clawed frog ifnl3 (26% identical), tropical clawed frog ifnl3.4 (24% identical), tropical clawed frog ifnl2 (23% identical). Paralogues in human: IFNL2 (96% identical), IFNL1 (72% identical).
Diseases named in the same sentence as IFNL3 in open-access papers:
IFNL3 is named in the same sentence as 117 diseases in open-access papers, as found by Europe PMC text mining. Sharing a sentence is not in itself a finding about the gene and the disease. The quoted sentences say what the papers report.
chronic hepatitis C (101 papers, 2011 to 2024). "Major alleles of IFNL3 are associated with less pronounced disturbances of lipid metabolism and less frequent steatosis and insulin resistance in chronic hepatitis C patients." (PMID 28525983, 2017). "Several papers have reported that genetic polymorphisms near the IL28B gene, encoding interferon-lambda-3, influence the response to treatment in chronic hepatitis C." (PMID 22368681, 2011). "The SNPs in the region of IFN-λ are associated with the standard treatment response for chronic hepatitis C as well as with the spontaneous HCV clearance, as IFNL3 SNPs, are considered the strongest predictors upon antiviral therapy response." (PMID 34307188, 2021). "In our previous study, we proposed a simple tool for the prediction of spontaneous resolution and chronic hepatitis C based on IFNL3 genotype and genetic profiles (GUP/GFP) using a combination of HLA-B, HLA-C, and KIR genes." (PMID 33624609, 2021). "The factors analyzed in our previous study using conventional univariate and multivariate analysis showed that there was a strong association between IFNL3, HLA-B*44, KIR3DS1, and HLA-C*12 and the probability of developing chronic hepatitis C." (PMID 33624609, 2021). "In this study, we compared the role of IFNL4 variants with IFNL3-(rs12979860) and IFNL3-(rs8099917) on response to pegylated (PEG)-IFN and Ribavirin (RBV) in patients with chronic hepatitis C GT2/3." (PMID 26699619, 2015). "Our study aimed at exploring IFNL3 gene expression in clinical samples, i.e., in ex vivo derived liver tissue from patients with chronic hepatitis C (n = 57) and various other diseases (n = 56)." (PMID 26606750, 2015). "Common single nucleotide polymorphisms (SNPs) in the IFNL3, IFNL4 and the IFNL receptor α-subunit genes have been strongly associated with IFN-α-based treatment of chronic hepatitis C virus infection." (PMID 26038748, 2014). "However, chronic hepatitis C infection occurs in numerous women carrying favorable IFNL3 genotypes, indicating that other host and/or virological factors contribute to the prognosis of infection." (PMID 29866105, 2018). "Interferon lambda 3 (IFN-λ3) is a newly identified cytokine with antiviral activity, and its single nucleotide polymorphisms are strongly associated with the treatment effectiveness and development of chronic hepatitis C virus infection." (PMID 22558263, 2012). "To better understand the dynamics between type I and III IFNs expression in chronic hepatitis C patients, we also quantified the expression of IFNA1, IFNL1, IFNL2, IFNL3 and IFNL4 in 24 healthy volunteers." (PMID 34307188, 2021). "However, many females carrying favorable IFNL3 genotypes suffer from chronic hepatitis C in China, indicating that besides IFNL3 genotypes and possibly some KIR/HLA alleles, other immune-related factors associated with HCV spontaneous clearance still remain unknown." (PMID 29866105, 2018). "Single nucleotide polymorphisms (SNPs) within DNA region containing interferon lambda 3 (IFNL3) and IFNL4 genes are prognostic factors of treatment response in chronic hepatitis C (CHC)." (PMID 27125837, 2017). "This investigation aimed at validating the impact of IFNL3 rs4803217 and IFNL4 rs368234815 genotypes on hepatic IFNL3 mRNA expression in clinical samples in chronic hepatitis C in man." (PMID 26606750, 2015). "A previous analysis of hepatic IFNL2/IFNL3 transcripts in chronic hepatitis C patients was carried out covering them both and did not reveal any induction by chronic HCV infection in patient livers." (PMID 26606750, 2015). "Another limitation is, that IL28B (IFNL3) testing was not part of the study protocol as the study was initiated before the discovery that IL28B is predictive for IFN response in chronic hepatitis C." (PMID 26057627, 2015).
hepatitis C (85 papers, 2011 to 2026). "Many studies have identified IFNL3 polymorphisms to be correlated with the outcome of hepatitis-C infection." (PMID 35784542, 2022). "Many associations have been found between interferon lambda 3 rs12979860 polymorphism and various clinical outcomes as a control of the hepatitis C virus infection, myeloproliferative neoplasms, dengue virus in children and systemic lupus erythematosus." (PMID 34071309, 2021). "Indeed, GWAS have yielded important pharmacogenetic findings (for example, identifying IFNL3/IL28B gene polymorphisms associated with interferon/ribavirin response in hepatitis C therapy) that later became features in machine learning models." (PMID 41304894, 2025). "The IFNL3 polymorphisms predict response to treatment in patients with hepatitis C." (PMID 29562888, 2018). "This was followed by the genotypes of IFNL3, which are predicted to produce an unfavorable response to treatment for Hepatitis C in 52.5% of the population studied (Hom alt: 10.4%; Het: 42.2%)." (PMID 35169154, 2022). "For patients with hepatitis C treated with pegylated interferon-alpha, the IFNL3 genotype is the strongest pretreatment predictor of drug response." (PMID 34306260, 2021). "In conclusion, a clear correlation exists between the IFNL3 genotype and the biochemical phenotype of patients of European descent infected with hepatitis C, including the levels of GGT, ALT, and cholesterol." (PMID 24204859, 2013). "Genotyping for four SNPs in the IFNL3 (IL28B) gene locus was undertaken based on literature supporting their role in predicting viral clearance for hepatitis C infection and NMR-based urine metabolomics, which have shown promise in predicting response in rheumatoid arthritis." (PMID 40606851, 2025). "Alternatively, the new hepatitis C therapies such as sofosbuvir, ledipasvir, and daclatasvir, which are not known to be affected by the mutations in IFNL3 and IFNL4 genes, can be used." (PMID 36388934, 2022). "Recently, a polymorphism in the interleukin-28B (IL28B) gene region, encoding interferon-lambda 3, was identified as a strong predictive factor for response to antiviral treatment in nontransplant patients with hepatitis C." (PMID 23505497, 2013). "This method is also applicable to the production of human Interferon Lambda-3 (IFN-lambda 3), a candidate biopharmaceutical compound against hepatitis C infection." (PMID 37500719, 2023). "Genome-Wide Association Studies (GWAS) identified genetic variations upstream of IFNL3 (IL28B) that are effective biomarkers for predicting spontaneous and interferon-alpha/ribavirin treatment-dependent cures of Hepatitis C virus infection." (PMID 35481423, 2022). "The authors demonstrated slightly higher IFNL2/IFNL3 mRNA expression in the liver of hepatitis C patients carrying the minor non-favorable IFNL4 rs12979860 C alleles." (PMID 26606750, 2015). "A common variant rs368234815TT/∆G creating functional gene from an IFNL4 pseudogene is associated with the expression of major ISGs in the liver but impaired clearance of hepatitis C. To explain this, we compared Halo-tagged and non-tagged IFNL3 and IFNL4 signaling in liver-derived cell lines." (PMID 33806448, 2021).
liver fibrosis (57 papers, 2011 to 2024). "The major IFNL3 rs12979860 CC genotype previously associated with liver fibrosis was present at a significantly higher frequency in SSc patients with pulmonary fibrosis compared to those without (29% vs 21%, OR: 1.51 (95% CI: 1.077–2.119, p = 0.01)." (PMID 31619697, 2019). "For instance, the levels of IFNL3 in serum have been found to be high in subjects with pulmonary fibrosis, resulting in the conclusion that this may be linked to both liver fibrosis and pulmonary fibrosis." (PMID 33092458, 2020). "However, other studies showed that the IFNL3 genotype were associated with the risk of developing advanced liver fibrosis or severe necroinflammation." (PMID 28797039, 2017). "Growing interest in exploring the role of IFN λ in liver fibrosis has stemmed from the discovery of an association between IFN λ SNPs and major IFNL3/IFNL4 with HCV clearance." (PMID 39201329, 2024). "To date, the best baseline predictors for HCV therapy are HCV genotype, HCV viremia, liver fibrosis and single-nucleotide polymorphisms around the interferon lambda 3 (IFNL3) gene, also known as interleukin 28B (IL28B)." (PMID 25367448, 2014). "In conclusion, IFNL3 serum levels and the genetic variant known to be associated with liver fibrosis are similarly linked to PF, but not to worsening of skin fibrosis in SSc." (PMID 31619697, 2019).
Cirrhosis (45 papers, 2011 to 2024). A chronic disorder of the liver in which liver tissue becomes scarred and is partially replaced by regenerative nodules and fibrotic tissue resulting in loss of liver function. "In conclusion our study highlighted the importance of geographical difference in the frequencies of PD-1 and IFNL3 genetic polymorphisms in HCV-related diseases particularly in cirrhosis and in HCC susceptibility." (PMID 30930876, 2019). "With regards to baseline characteristics, we determined a statistically significant association of both older age and IFNL3 CC genotype with cirrhosis in the cohort." (PMID 27711230, 2016). "In line with our study, some researchers have shown an association between the major homozygous IFNL3 genotype (rs12979860 CC or rs8099917 TT) with severe portal inflammation, hepatic necroinflammation, fibrosis and cirrhosis." (PMID 27711230, 2016). "The association of IFNL3 genotype and cirrhosis condition is also noteworthy in the present cohort." (PMID 27711230, 2016). "Compared to the non-SVR patients (n = 92), the SVR patients (n = 427) exhibited lower HCV RNA, HOMA-IR, and C-peptide levels, lower genotype 1 HCV infection and cirrhosis rates, a higher rate of the IFNL3-rs12979860 CC genotype, and higher platelet counts." (PMID 33446046, 2021). "Compared with those who did not achieve SVR, lower HCV RNA level, HOMA-IR score, and G1 HCV infection and cirrhosis prevalence rates, as well as higher platelet counts and interferon-λ3 (IFNL3) CC genotype frequency were observed in SVR patients." (PMID 28574439, 2017). "It has been suggested that IFNL3 CC homozygotes, in whom treatment response rates are higher, but progression to cirrhosis may occur more rapidly would benefit the most in early access to treatment." (PMID 27711230, 2016). "Comparison of IFNL3 T-allele distribution between groups of patients affected by different HCV-related liver diseases and healthy BD underlined the role of such polymorphic variant as dominant key factor for the progression of cirrhosis to the most advanced liver diseases in our series." (PMID 30930876, 2019). "However, many other researchers believed that achieving SVR is a multifactorial event that could be affected by host factors such as liver conditions (cirrhosis), the previous history of IFN-based treatment, the existence of some IFNL3/4 polymorphisms, and consuming alcohol." (PMID 33584581, 2020). "In particular, patients with more advanced HCV-related liver diseases (i.e., cirrhosis and HCC) the frequency of IFNL3 T/T homozygous genotype was 1.4-fold higher than in MC and NHL, and 3.3 higher than in BD." (PMID 30930876, 2019). "More studies were identified for IFNL3/IFNL4 than any other gene, with seven original studies (with a total of 3,154 patients) and three meta‐analyses using HCC as an outcome and six using cirrhosis or fibrosis." (PMID 29397014, 2018). "The proportion of individuals who developed cirrhosis in the IFNL3 CC group (41.3%) was significantly higher than the non-CC group (19.4%, P = 0.008)." (PMID 27711230, 2016). "We therefore suggest that the preferred patient populations for IFNL3 testing are naïve genotype 2 and especially naïve genotype 3 patients with low baseline viremia and without signs of cirrhosis." (PMID 26699619, 2015).
viral infection (33 papers, 2012 to 2026). "Viral infection was more consistently associated with IFNL3 with approximately 95% of patients with either SARS-CoV-2 or HCV having detectable amounts of plasma cytokine compared with 37% of healthy donors." (PMID 38953458, 2024). "Among 98 specific DEGs in JEG-3 cells, IFNL3 encodes a cytokine distantly related to type I interferons, and can be induced by viral infection." (PMID 36209057, 2022). "We revealed that IFNL3 favorable genotypes could increase the risk of dyslipidemia, which is opposite to its beneficial role observed in viral diseases." (PMID 35784542, 2022). "Variants in interferon lambda genes, such as IFNL3 (formerly IL28B), can impact the efficacy of the interferon response against viral infections." (PMID 39796114, 2024). "At the onset, IFNL3 possesses anti-tumorigenic and immune-modulatory effects and is primarily triggered by viral infections." (PMID 33092458, 2020). "IFNL3, a member of the interferon lambda family, has immune-modulatory and anti-tumorigenic effects and is induced by viral infections." (PMID 29562888, 2018). "It is also possible that the decreased circulating IFNL3 facilitates viral infection leading to less Pro-C3 which results in worse lung function and shorter time to exacerbation." (PMID 29562888, 2018). "Although the mechanisms and role of IFNL3 genotype in viral control and outcome of HCV infection are not fully understood, there is evidence that IFNL3 regulates the interferon stimulated genes (ISGs), required for initial control of viral infection." (PMID 25837807, 2015). "IFNL3 has immune-modulatory and anti-tumorigenic effects and is induced by viral infections." (PMID 29562888, 2018). "In particular, IL-28B, called interferon lambda 3 (IFN-λ3), plays a critical role in the innate immune response against viral infections." (PMID 40430790, 2025). "Interferon lambda (IFNL), which expresses IL28B (IFNL3), plays an important role in viral infections." (PMID 32099617, 2019). "The AUC-ROC was 0.881 for IFNL3 rs12979860, 0.748 for IFNL3 rs8099917, 0.726 for IFNL3 rs12980275, and 0.869 for IFNL4 rs368234815, suggesting that host genetic factors are generally important for the resolution of viral infection." (PMID 34775984, 2021). "The modulation of IFNL expression by SNPs in the IFNL3/4 gene region and IL28RA signaling cascade may potently affect Th1 and Th2 cytokine production and memory formation during viral infections." (PMID 26038748, 2014).
liver disease (26 papers, 2011 to 2024). "The frequency of IFNL3 T allele was also higher in patients with hepatic diseases compared to the lymphoproliferative diseases (MAF 0.44 vs. 0.36; OR = 1.77, 95%CI 1.40–2.25, p < 0.0001)." (PMID 30930876, 2019). "In the present study we demonstrated that the multilocus TLR2-ins/ IFNL3 T genotype was a significant factor for development of HCV-related liver diseases, and that the impact of rare PD-1.6 variant in Italian population is responsible for the discrepancy between Asian and European results." (PMID 30930876, 2019). "The authors explained that this result may have been related to the IFNL3 gene polymorphism, which is another factor associated with the severity of liver disease in CHC." (PMID 28797039, 2017).
co-infection (24 papers, 2011 to 2025). "It is reported that among host factors, gender, age, IFNL3 (previously IL28B) genotypes, KIR/HLA alleles, ethnicity, and HIV co-infection are associated with spontaneous recovery." (PMID 29866105, 2018). "Baseline characteristics of IFNL3-spontaneous clearance study population compared with the Canadian Co-infection Cohort (CCC) source population." (PMID 25803108, 2015).
hepatocellular carcinoma (22 papers, 2012 to 2024). A malignant tumor that arises from hepatocytes. "IFNL3 rs12979860 and rs8099917 polymorphisms have been found to affect the risk of hepatitis virus-related hepatocellular carcinoma." (PMID 28525983, 2017). "Due to experiments on human hepatoma cells which were transfected with allelic IFNL3 constructs, its T allele was shown to promote decay of IFNL3 mRNA by two mechanisms." (PMID 26606750, 2015). "SNP in genes, such as PPP1R15A, PLA2G4C, CMTM8, and IFNL3, are responsible for the growth of various cancers, such as colorectal cancer, osteosarcoma, and hepatocellular carcinoma, but SNP in these genes may be associated with the pathogenesis of BRCA." (PMID 31311202, 2019). "We also tested the IFNL3 reporter constructs in an immortalized human hepatocyte cell line (PH5CH8), a human hepatoma cell line (LH86), and HeLa cells by transient plasmid transfection." (PMID 26531896, 2015). "Hepatoma cell lines and PHH have also been used to study how the IFNL subtypes differ in their ability to limit viral infections; IFNL3 and IFNL4 induce the same set of ISGs in PHH and the two subtypes have the same antiviral activity against HCV in an overexpression setup in hepatoma cells." (PMID 28255563, 2017).